NIFK-AS1 (NIFK antisense RNA 1)
Gene: Long non-coding RNA gene on chromosome 2 (121,649,320 to 121,728,567, forward strand). Ensembl gene ENSG00000236859.
Gene Ontology:
Biological process: RNA processing
Cellular component: nucleolus